KL (klotho)
Diseases named in the same sentence as KL in open-access papers (continued):
Sharing a sentence is not in itself a finding about the gene and the disease.
kidney disease (continued). "Therefore, retarding the decline in Klotho expression or upregulation of endogenous Klotho are plausible strategies to eliminate or suppress kidney disorders." (PMID 35299661, 2022). "In contrast, those with severe renal disease had unchanged Klotho levels." (PMID 35903083, 2022). "Klotho is a pleiotropic protein that exhibits multifaceted functions related to kidney diseases." (PMID 36434087, 2022). "The strong relationship between s-Klothoand UA implies that s-Klotho may be indicative of the diseases involving UA, for example in kidney diseases, because both have been described as predictive markers of renal function." (PMID 35603960, 2022). "Notably, adipose-tissue-derived MSCs (AT-MSCs) injected into animals with streptozotocin-induced renal injury, e.g., DKD, prevented the progression of kidney disease by decreasing Bax and Wnt/β-catenin levels, and increasing Bcl-2 and Klotho levels." (PMID 35056905, 2021). "Low levels of Klotho occur in neurodegenerative diseases, kidney disease and many cancers." (PMID 31929539, 2020). "Therefore, understanding the mechanism and the factors controling the shedding of Klotho in different tissues can result in potential therapeutics for kidney disease." (PMID 31929539, 2020). "Klotho DNA hypermethylation plays critical roles in the pathogenesis of kidney diseases." (PMID 32908633, 2020). "We excluded patients with advanced kidney disease and those on treatment with vitamin D, calcium or phosphate supplements or binders as this may influence Klotho and FGF23 levels and could confound interpretation of the results." (PMID 33225726, 2020). "Recent studies have shown that Klotho plays an important role in the development of kidney disease." (PMID 32908633, 2020). "Furthermore, Klotho is predominantly localized in kidneys, which implies that among the potential therapeutic applications of Klotho, kidney diseases should be a particular focus." (PMID 31318148, 2019). "However, KLOTHO overexpression exhibited a protective effect in various rodent models of renal diseases as well as heart diseases." (PMID 31199854, 2019). "As Klotho, a kidney-protective factor, is reduced, Klotho replacement therapy may have beneficial effects for kidney diseases." (PMID 31024315, 2019). "Klotho is upregulated by resveratrol, testosterone, statins, Rhein, and hydrogen-rich saline in both the cells and tissues of animals with kidney disease." (PMID 31680971, 2019). "For these reasons Klotho may serve as a beneficial factor in the kidney diseases and in the uremic cardiomyopathy as well." (PMID 30671457, 2018). "Moreover, our results also contrast with previous reports in other renal diseases, where plasma, renal and urinary Klotho go in the same direction, considering that serum and urinary Klotho can be surrogate markers for renal Klotho production." (PMID 30483154, 2018). "As reduced Klotho expression level in the kidney may sensitize the kidneys to injury and aggravation of renal interstitial fibrosis, hence accelerating renal disease progression, a vicious cycle may ensue." (PMID 30208590, 2018). "There is a link between Klotho deficiency and CKD, renal disorders, and kidney damage." (PMID 30671457, 2018). "It is known that Klotho is expressed mainly in the kidney and kidney disorders may contribute to disrupted expression of renal Klotho." (PMID 30671457, 2018). "In recent years, the roles of klotho in DM and renal diseases have attracted increased attention." (PMID 26813039, 2016). "In conclusion, our results favor the hypothesis that renal Klotho synthesis diminishes early in renal disease and that s-Klotho proportionally lessens; bone detects these changes somehow and increases FGF23 production." (PMID 25873958, 2015). "Besides mineral metabolism, Klotho FGFR1c-FGF23 axis is considered to be a predictor of progression of kidney disease and to be related to morbidity and mortality." (PMID 25295189, 2014).
kidney disease (continued). "The clear mechanism involved in the decrease of KL expression in kidney diseases is presently unknown, but this may potentially include ischemia, oxidative stress, uremic toxins, inflammation, and disordered metabolic conditions." (PMID 24224012, 2013). "We performed a Pub Med/Medline search for the terms Klotho, cardiovascular disease, and renal disease from 2000 to 2010 with a focus on recent mechanistic and proof-of-concept studies evaluating the role of Klotho in the prevention and treatment of cardiorenal disease." (PMID 22121479, 2012). "In view of the versatile health-beneficial effects of Klotho, spironolactone-dependent Klotho upregulation also makes perfectly sense as spironolactone has been shown to favorably influence heart disease and renal function at least in some models of kidney disease." (PMID 41301427, 2025). "Additionally, Klotho plays an essential protective role in kidney disease." (PMID 38584258, 2024). "Therefore, Klotho is postulated as a very promising new target for future therapeutic strategies against oxidative stress, mitochondria abnormalities, and cellular senescence in kidney disease patients." (PMID 36829798, 2023). "Thus, low Klotho levels are likely to be a reflection of renal disease, and if the renal mass is very low then any drug treatment might fail to increase Klotho." (PMID 35903083, 2022). "Therefore, klotho is considered a key target for the treatment of kidney disease." (PMID 35820962, 2022). "Therefore, the estimation of serum Klotho protein due to calcium and sodium dysregulation in renal diseases and the novel link between FGF23 and the metabolism of these ions may have major pathophysiological implications in CKD." (PMID 35812534, 2022). "However, the molecular mechanism underlying Klotho deficiency in kidney diseases is still not yet fully understood, leading to intensive ongoing research in this area." (PMID 35165517, 2022). "Furthermore, overexpression of the KL gene or administration of KL offers beneficial effects in rodent models of various renal diseases, including db/db mice, suggesting that induction of KL could be a novel therapeutic strategy for treating DN." (PMID 35992154, 2022). "However, the mechanisms that modulate klotho expression in renal diseases remain to be elucidated." (PMID 26813039, 2016). "Klotho is a potent therapeutic target regarding the different stages of CKD and a decline of its expression has been reported during renal disease progression." (PMID 33869246, 2021). "As renal disease progressed, despite the increasing FGF23 levels, fractional phosphorus excretion decreased possibly due to a lower renal Klotho expression and a reduction in functioning nephrons, with the net result of increased serum phosphate levels." (PMID 23967103, 2013). "Therefore, several findings support the potential safeguarding function of exogenous Klotho in DKD and various kidney diseases." (PMID 40119098, 2025). "However, iPTH, phosphate, and calcium correlated only with the renal disease progression, while FGF-23 and klotho were affected by CKD and CVD." (PMID 40002748, 2025). "Urinary klotho has potential as a biomarker of kidney disease or its progression, due to differences between stages of CKD disease and correlations with other parameters indicating kidney disease in previous studies." (PMID 39113723, 2024). "Low plasma, but not urine, levels of Klotho predicted the progression of nephropathy in T2DM patients and were negatively correlated with a decrease in the glomerular filtration rate (GFR)." (PMID 33478014, 2021). "The compensatory production of Klotho, thus renoprotection, has not been found also in renal disorders." (PMID 32319182, 2020). "Our data indicate a negative effect of renal disease on circulating s-Klotho starting very early in CKD." (PMID 25873958, 2015).
kidney disease (continued). "Recent data support this hypothesis as changes in Klotho levels appear to precede changes in phosphate levels, the key driver of FGF23 balance in renal disease." (PMID 22121479, 2012). "Non-epigenetic factors contribute to the downregulation of Klotho in kidney disease." (PMID 40799848, 2024). "In the context of kidney disease, PTX has been shown to prevent the decline of important cellular proteins, like Klotho, which may provide a clue that its anti-inflammatory effects could extend to the protection of phospholipid layers like those in the gastric mucosa." (PMID 39765810, 2024). "The Klotho gene has been regulated by epigenetic and non-epigenetic mechanisms in renal disease." (PMID 37228732, 2023). "In virtually all kidney disease models including UUO, DN, adriamycin nephropathy, remnant kidney after 5/6 nephrectomy (5/6NX), ischemia/reperfusion injury (IRI) and cisplatin nephropathy, the expression of Klotho is markedly decreased in serum and the kidneys." (PMID 33362554, 2020). "Thus, there is no renoprotection due to reduced expression of renal Klotho in the state of kidney disorders." (PMID 32319182, 2020). "Second, although the Klotho protein analysis detected without the collection of urine samples from the pregnant women in many studies, the mechanism of whether the decreased of the Klotho protein was related to renal diseases should be further studied." (PMID 40831795, 2025). "Moreover, as MSCs do not express Klotho it would be possible to combine Klotho’s antioxidant effects through gene therapy and the protective properties of MSCs, representing a strategy to both treat kidney diseases and preserve the therapeutic potential of MSCs." (PMID 35056905, 2021).
tumor (117 papers, 2009 to 2026). "Most published studies have described the loss of Klotho protein expression in human tumor tissues, but there is a relative paucity in the data relating to serum Klotho in solid tumors." (PMID 39796185, 2025). "In tumors, Klotho expression is reduced in the majority of tumor samples, and low Klotho expression in tumors is associated with poorer overall survival." (PMID 40134808, 2025). "Structural modeling and mutation studies revealed that mutated KL proteins maintained their tumor suppressor activity despite a reduced ability to influence FGF23 signaling." (PMID 40004457, 2025). "α-Klotho is linked to a tumour suppressor, β Klotho is related to both tumorigenic and tumour-suppressive actions in several cancers, exhibiting more complicated activities, and γ Klotho expression has been investigated in different forms of cancer." (PMID 40119098, 2025). "Klotho protein is discovered as a universal tumor suppressor, and its expression is associated with tumorigenesis and prognosis of patients." (PMID 37488085, 2023). "Based on previous studies showing PDAC development in mice harboring both Kras mutation and loss of tumor suppressor activity, we examined Pdx1-Cre; KL−/−; KrasG12D/+ mouse pancreata for lesions." (PMID 34944918, 2021). "In contrast to the sizeable body of literature describing the loss of Klotho protein expression in human tumour tissues, there is a relative paucity in published data relating to circulating Klotho in solid tumours." (PMID 32585905, 2020). "Higher KL gene expression is again associated with better survival, and KL methylation with gender, tumor grade, and site." (PMID 33520985, 2020). "These technological developments address ways in which methylation can be reversed and have the potential to provide a therapeutic advantage in tumours that display loss of Klotho protein expression." (PMID 32585905, 2020). "sKL is associated with high tumor grade, suboptimal tumor debulking results, disease progression [hazard ratio (HR) = 1.97], and death (HR = 2.09), possibly due to KL supporting the tumor with energy and angiogenesis." (PMID 33520985, 2020). "In summary, Klotho appears to be a tumor suppressor; loss of klotho, readily evident during cancer progression, promotes migration, invasion and tumor growth via activation of growth factor signaling pathways (e.g., Wnt and TGF-β1)." (PMID 29799477, 2018). "They found atractylodin enhanced the ghrelin-induced Ca2+ fluorescence in GHSR-expressing cells, prolonged the survival of tumor-bearing rats, and alleviated age-related diseases in klotho-deficient, SAMP8, and aged ICR mice." (PMID 28883883, 2017). "However, klotho also participates in multiple pleiotropic activities that are tightly associated with cancer and was discovered as a universal tumor suppressor." (PMID 39796185, 2025). "It has been found that Klotho gene polymorphisms are associated with tumor development and growth." (PMID 39287231, 2024). "Further clinical development of Klotho-based assays will require careful identification of specific tumor subtypes where Klotho proteins may be most valuable as diagnostic or prognostic tools." (PMID 37958253, 2023). "Furthermore, Klotho overactivity causes a decline in the lifespan of malignant cells, and therapy with soluble Klotho leads to tumor density suppression in presymptomatic models of carcinoma." (PMID 37425590, 2023). "When KEAP2 mutations are concomitant with KL mutations, accelerated tumor growth is observed." (PMID 35573694, 2022). "Tumor suppressor capabilities of KL have been implicated in numerous cancer types." (PMID 35468874, 2022). "Therefore it was concluded that downregulation of Klotho was associated with overexpression of DNMT3B in tumor tissues." (PMID 33369458, 2020). "Thus, higher KL expression is associated with cirrhosis, venous invasion, tumor multiplicity, and a lower overall survival in HCC patients according to this study." (PMID 33520985, 2020).
tumor (continued). "This turns Klotho into a potential clinical biomarker in high-grade LPS and suggests that its loss could be a selective advantage for tumor development." (PMID 30441794, 2018). "Meanwhile, considering our observations at the transcriptomic level, KL downregulation may represent a selective advantage for tumor cells and so, may be associated with tumor evolution as for DDLPS." (PMID 30441794, 2018). "Finally, the klotho gene encoding the obligate co-receptor for FGF-23 is also a putative tumour suppressor gene, further implying the link between Pi regulation and carcinogenesis." (PMID 23706176, 2013). "However, more research is needed to determine whether klotho’s association with tumor suppression is mediated by klotho’s role in downregulating Pi concentrations in cancer cells in vivo." (PMID 36557322, 2022). "Most articles describe KL as a tumor suppressor, but it also shows pro-tumoral effects that “increases cellular migration, anchorage-independent growth, and anoikis resistance in hepatoma cells”." (PMID 41596231, 2026). "KL (Klotho): The KL gene was identified in 1997 as an anti-aging gene and was initially believed to be a tumor suppressor gene/protein." (PMID 41596231, 2026). "In conclusion, Klotho has emerged as a potent tumor suppressor that acts by modulating vias related to cancer cell growth and survival, regulating epigenetic mechanisms, and increasing sensitivity to chemotherapy." (PMID 40004457, 2025). "Treatment of the KL model with GSK2879552 significantly inhibits KL tumor progression and neutrophil infiltration." (PMID 40568576, 2025). "The authors found that serum Klotho had a tumor suppressor effect, and a higher level of Klotho concentration had a stronger effect." (PMID 39796185, 2025). "Studies in animal models and cell cultures have demonstrated that KL overexpression significantly reduces tumor proliferation and promotes apoptosis." (PMID 40004457, 2025). "Klotho is a tumor suppressor gene with significant roles in inhibiting the progression of various cancers." (PMID 40004457, 2025). "Histological analysis revealed hepatocellular atrophy, apoptosis, Kupffer cell hyperplasia and neutrophil infiltration in KL tumour‐bearing mice." (PMID 40702652, 2025). "IL‐6 expression in the spleen differed by sex: in females, only KL tumours bearing mice showed IL‐6 upregulation, whereas in males, K tumours bearing mice showed IL‐6 upregulation." (PMID 40702652, 2025). "Generally, the KL promoter is hypermethylated in tumor tissues, with a consequent decrease in the KL expression." (PMID 40006994, 2025). "In these malignancies, lower expression of Klotho often correlates with poorer prognosis, increased tumor aggression, and reduced survival rates." (PMID 41261673, 2025). "The abemaciclib-treated patients with samples characterized as KL by both mutation- and expression-based subtyping (n=10) had an average PFS of 8.42 months, and only 2 patients had an increase in tumor size." (PMID 40231258, 2025). "It was also suggested that Klotho acts as a tumor suppressor and an inhibitor of the Wnt/β-catenin pathway in HCC46." (PMID 38267588, 2024). "Utilizing KL and KP mouse model, we identified KL tumor as “immune-cold” tumor with excessive ECM collagen deposition that formed a physical barrier to block the infiltration of CD8+T cells." (PMID 38291516, 2024). "Klotho served as a potential tumor suppressor in a variety of tumors, inhibited cell proliferation and induced tumor apoptosis." (PMID 38482526, 2024). "G6PD expression was completely deleted in KP and KL lung tumors, which was validated by immunohistology (IHC) and mRNA expression from KL bulk-tumor mRNA-seq." (PMID 38997257, 2024). "Combined inhibition of KRASG12C and ULK1/2 decreases tumor initiation and increases survival in KL genetically engineered mouse (GEM) models." (PMID 39213022, 2024).